GZMB (granzyme B)
Diseases named in the same sentence as GZMB in open-access papers (continued):
Sharing a sentence is not in itself a finding about the gene and the disease.
tumor (continued). "GZMB is highly expressed by cytolytic CD8+ T cells, natural killer (NK) and γδT cells to eliminate pathogenic and tumor cells and SERPINB9 is usually expressed in these cytolytic effector cells to protect them from apoptosis induced by their own GZMB57–59." (PMID 37258521, 2023). "Immunofluorescence staining of caspase 3 after [131I]-KN046 treatment demonstrated expression of granzyme B. This result also showed the same trend as that of [68 Ga]-NOTA-GZP uptake at the tumor site." (PMID 36242616, 2023). "SC144@HABN treatment also induced proliferation (Ki67+) and activation (granzyme B+) of tumor-infiltrating CD8+ T-cells, as compared with SC144 treatment (p < 0.01)." (PMID 37553327, 2023). "Meanwhile, the numbers of CD8+ T cells, proliferated CD8+ T cells, and activated CD8+CD69+ T cells, CD8+IFNγ+ T cells and CD8+GzmB+ T cells were the highest in tumor tissues of R848@M2pep-MPsAFP and anti-PD-1 antibody-treated group." (PMID 37704614, 2023). "Exosomes-derived NK cells (NK-exos) are enriched with specific cytotoxic proteins, including granzyme B and perforin, which exhibit tumor-killing abilities against cancers." (PMID 37484408, 2023). "Cisplatin and doxorubicin have been shown to sensitize the most resistant colon cancer cell lines to TRAIL-induced cell death, and cisplatin, doxorubicin, and paclitaxel sensitize tumor cells to CTLs by making tumor cells permeable to granzyme B in mice." (PMID 37296876, 2023). "In particular, the limited co-occurrence of granzyme B and perforin restrains serial killing of tumour cells by γδ T cells." (PMID 37758698, 2023). "Granzyme B has been shown to be involved in tumor suppression by activating gasdermin E, which is involved in cellular pyroptosis, and is also known to play an important role in tumor immunity." (PMID 37298408, 2023). "Among the most significantly upregulated proteins in the tumor periphery was granzyme B. Granzyme B upregulation in the tumor periphery correlated with a significantly reduced cancer-specific patient survival." (PMID 37894418, 2023). "The EVs from activated NK cells include a variety of Gzms, such as GzmA and GzmB, which have cytotoxic effects on tumor cells, inhibit cell proliferation, and promote cell death." (PMID 36875082, 2023). "For example, CD8+T cells exerted an important role in immune surveillance and anti-tumor response through secreting multiples of cytokines such as perforin, granzyme B." (PMID 36662756, 2023). "Mice treated with the combination of ICIs and FMD showed only a trend for increased accumulation of cytotoxic NK cells (CD45+Nkp46+GzmB+) inside the tumor and increased expression of CD127 by CD8+CD44+ effector T cell compared to ICI alone." (PMID 37684243, 2023). "The levels of granzyme B in the tumor-specific CD8+ T lymphocytes were lower during 24 h incubation but were found to be increased after 48 h of incubation." (PMID 36944686, 2023). "ICI ultimately works by promoting activation of CD8+ T cells to produce and release granzyme B resulting in tumor cell toxicity." (PMID 35890355, 2022). "This group not only confirmed this expression but also found that this GzmB and Prf-1 secretion is essential for tumor growth." (PMID 35326588, 2022). "This form of proinflammatory cell death can be induced by the cleavage of gasdermin E and B by granzyme B and A, respectively, which are delivered into tumor cells via the action of perforin." (PMID 35503659, 2022). "Granzyme B activates GSDME which is widely expressed on CD19 positive malignant B cells, resulting in tumor cell pyroptosis and the release of danger associated molecular patterns (DAMPs), such as high-mobility group box 1 (HMGB1)." (PMID 35757715, 2022). "The level of IFN-γ, perforin, and granzyme B were determined by ELISA and Real-time PCR assays, while tumor-infiltrating T cells were measured by flow cytometry and immunohistochemical analysis." (PMID 36544785, 2022).
tumor (continued). "CXCL10, in addition to inducing effector Th1 cells, also recruits CXCR3+CD8+ T cells to tumor sites and induces granzyme-b production through these cells, thereby enhancing the anti-tumor effect." (PMID 36479091, 2022). "Following this, the expression of TNF-α, IFN-γ, perforin, and granzyme B in the peripheral blood of tumor-bearing C3H mice was detected by ELISA." (PMID 35115487, 2022). "CTLs and NK cells destroy tumor cells by releasing perforin and granzyme-B, as well as interacting with death receptors (such as tumor necrosis factor-related apoptosis-inducing ligand [TRAIL]) on the cell surface." (PMID 36080223, 2022). "Previous immune-related analyses in this paper showed that CHMP4C, TNF, and GZMB are all closely related to the tumor immune microenvironment." (PMID 35574296, 2022). "We observed increased staining for granzyme B in PBMCs incubated with tumour organoids compared to those incubated with healthy organoids." (PMID 36237445, 2022). "In summary, a PET radiotracer, 68Ga-grazytracer, was designed to specifically target granzyme B and monitor the efficacy of multiple immunotherapies in different tumor mouse models." (PMID 35788116, 2022). "Classification of tumors as responders based on eventual changes in tumor volume revealed granzyme B PET imaging to be highly sensitive and selective for treatment response." (PMID 35214172, 2022). "Specifically, different Vδ2+ cell phenotypes post-expansion preferentially produced either granzyme B or granzyme K in responses to tumour cell lines, differentially affecting their ability to lyse a range of tumour cell lines." (PMID 35404420, 2022). "CD8+ T cells develop into cytotoxic T lymphocytes (CTL) and eliminate tumor cells by releasing cytotoxic mediators, such as granzyme B (GzmB) and granulysin (Gnly)." (PMID 36387070, 2022). "To assess the involvement of granzyme B in the elevated level of tumour cell killing seen post MB-PDT, we used a substrate-specific GrzB fluorescent probe H5." (PMID 36077656, 2022). "Ligand-bound NKG2D induces cytolytic functions of γδ T cells via granzyme B and perforin secretion to mediate tumor cell killing." (PMID 35880177, 2022). "The level of granzyme B, mainly originating from CTLs in our model, was significantly elevated in Gal1 vaccinated mice and correlated with a decrease in tumor burden." (PMID 35018481, 2022). "Among these, granzyme B has been studied as indicator of anti-tumor T-cell function and marker for PET imaging during immunotherapy." (PMID 35099641, 2022). "The levels of T cell activation markers CD69, IFN-γ, and GZMB in tumor-infiltrating CD8+ T cells were increased in sgRad21 B16-OVA tumors compared with scramble sgRNA–carrying tumors." (PMID 36201246, 2022). "In the current study, high BCAA increases the secretion of IFN-γ and granzyme B by NK cells in tumor-bearing mice." (PMID 35785192, 2022). "As the prime anti-tumor cells, CD8+ T cells can secrete IFN-γ and TNFα to destroy cancerous cells once they contact tumor cells or eliminate tumor cells by releasing perforin and granzyme B through the Fas/FasL pathway." (PMID 36132141, 2022). "Mechanistically, it has been demonstrated that CD8 + T cells and NK cells induce pyroptosis in tumor cells via granzyme B, thereby establishing a positive feedback loop, namely pyroptosis-activated immune microenvironment." (PMID 35000541, 2022). "On Day 4, compared with the control treatment, anti-PD-L1 treatment both with and without anti-VEGF treatment resulted in higher percentages of CD8+ T cells and GzmB+CD8+ T cells in tumor tissues in the HM-1 model." (PMID 34958105, 2022). "Among them, CD8+ T cells infiltrate tumors as a symbol of immune recognition and destroy tumor cells by secreting granzyme B, TNF, and IFNγ, indicating better survival in OC patients." (PMID 35837397, 2022).
tumor (continued). "When activated CD8+T cells bind specifically to tumor cells, and CD8+T cells release perforin and granzyme B perforin and granzyme B can perforate the target cells, destroy the integrity of the cell membrane, and then kill the tumor cells." (PMID 36359744, 2022). "The tumour reactivity of PBMCs-turned-CD8+ T cells was evaluated after 10 days of co-culture with cancer organoids by staining for granzyme B." (PMID 36237445, 2022). "•Granzyme B intracellular staining showed increased tumour reactivity in T cells co-cultured with cancer organoids compared to healthy controls." (PMID 36237445, 2022). "Tc17 cells (characterised by IL-17A, IL-17F, IL-21, IL-22 production and low levels of granzyme B) have been associated with both anti-tumour (esophageal SCC patients) and pro-tumour activity (HNSCC patients)." (PMID 35406451, 2022). "PRDM1 upregulation impaired the CD8+ T cell activation (CD8+GZMB+ T cells) and T cell-mediated tumor cell killing activity (CD8+TNFα+ T cells) in the co-culture, whereas PRDM1 knockout had contrasting effects." (PMID 36509766, 2022). "CAR T-cell therapy for cancer mainly induces caspase-3/GSDME-dependent tumour cell pyroptosis through the release of perforin and granzyme B." (PMID 35896522, 2022). "This additive effect was accompanied by increased expression of the cytotoxic molecule granzyme B and the cell proliferation molecule Ki-67 in tumor-infiltrating T cells, especially CD8+ T cells." (PMID 35514996, 2022). "It was demonstrated that the treatment reduced tumor growth and increased granzyme B and Ki-67 expression by tumor-infiltrating CD8+ T cells in MC38 colon-cancer-bearing mice compared with a combination of water and DICB." (PMID 36012249, 2022). "At the same time, how the activation of the downstream of LAYN affected other signal pathways, influencing the secretion of cytokines (such as IFN-γ, GZMB), and many other mechanisms that regulated anti-tumor immunity were worth of further investigation." (PMID 36260222, 2022). "These cells can directly induce tumor apoptosis via granzyme B (CTLs only) and production of IFNγ and TNFα, two cytokines which broadly reprogram the TME and can induce apoptosis in tumor cells." (PMID 35406557, 2022). "A recent study reported that tumor‐infiltrating Tregs of CRC express granzyme B (GZMB) immediately after tumor resection, while there are almost no GZMB‐expressing Tregs in tumor‐associated lymph nodes and circulating lymphocytes." (PMID 35474948, 2022). "This loss of effect was associated both with a reduction in tumour associated CD3+CD8+ T cells and loss of granzyme B+ immune clusters." (PMID 35477863, 2022). "To overcome the limitations of 18F-FDG, we explored the potential of 68Ga-grazytracer PET to distinguish tumor pseudoprogression from true progression via noninvasive imaging of granzyme B released by functional CTLs during ICI therapy." (PMID 35788116, 2022). "Consistently, we observed a more distinct immune phenotype at S2 tumours with reduced GZMB (granzyme B) and enriched PDCD1 (PD-1), FOXP3 and CTLA4 compared to N or S1 and S3 tumours." (PMID 35301339, 2022). "A potential role for granzyme B released from mast cells in the regulation of the extracellular matrix in vivo is the degradation of the extracellular matrix of tumours, thereby releasing FGF-1 and GM-CSF and promoting angiogenesis." (PMID 36342273, 2022). "We further investigated the capability of the probe H5 to detect GzmB activity in a mouse model of tumor regression." (PMID 35501326, 2022). "Though NK cells can kill target tumor cells by exocytosis of granzyme B, they also kill target cells by engaging death receptors such as FASL and TRAIL." (PMID 34999917, 2022). "Recent studies have proved that GzmB can further activate anti-tumor immune response and inhibit tumor growth by activating caspase-3/GSDME or directly cracking GSDME and inducing pyroptosis." (PMID 36138348, 2022).
tumor (continued). "In breast cancer patients, killer cell lectin-like receptor G1 (KLRG-1)+CD57+CD4+ and CD8+ senescent T cells that produce more effector cytokines, granzyme B and perforin accumulate in peripheral blood and in the tumor." (PMID 35326515, 2022). "NK cells in breast tumors express high levels of NKG2A and low levels of NKp46, perforin, and granzyme B. One week of treatment with IL-12 and anti-TGF-β resulted in the increased maturation of tumor-associated NK cells." (PMID 36601109, 2022). "We observed that the expression of NKG7, GZMH, GZMA and GZMB in tumor-infiltrating CD8+ CTSW+ cytotoxic cells were significantly increased in female patients, indicating that these T cells have a stronger antitumor cytotoxic effect." (PMID 36172359, 2022). "With respect to the granzyme B data, it cannot be concluded that this is due to the interaction between infused immune effector cells and tumor cells." (PMID 35243416, 2022). "For example, both mouse and human NKT cells can directly lyse tumor cells through a perforin-dependent mechanism, and the expression of granzyme B also enhances the killing effect of NK cells." (PMID 36119047, 2022). "Quantification of GZMB in tumor lysates confirmed increased production in the tumor microenvironment after DuoBody-CD3x5T4 treatment." (PMID 36271507, 2022). "Granzyme B and perforin are transported to target cells through immune synapses that are transiently formed between cytotoxic T cells and tumor cells." (PMID 35788116, 2022). "Within the TME, mavorixafor alone increased CD8+ T-cell infiltration, granzyme B signal, antigen presentation machinery, and both tumor inflammatory signature (TIS) and IFNγ gene expression signature scores." (PMID 36923305, 2022). "Here, the authors generate a fluorescent probe that can detect Granzyme B levels in tumours, and has the potential to be used as a biomarker of response to immunotherapy." (PMID 35501326, 2022). "This enhancement in CTL trafficking, in combination with increased class-I HLA expression within the TME, promotes effector–tumor cell interactions that increase granzyme B, IFNγ, and TIS gene expression." (PMID 36923305, 2022). "Mechanistically, we found that the combination therapy increased the number of Prf1- and GzmB-expressing CD8+ T cells, increased tumoral GzmB expression, and decreased tumor cell proliferation." (PMID 35380995, 2022). "In particular, interferon gamma (IFN-γ) and granzyme B are known to increase tumor immunogenicity, inhibit tumor cell proliferation, and enhance the cytotoxic function of natural killer (NK) cells and cytotoxic T lymphocytes (CTLs)." (PMID 36230744, 2022). "In hypoxic tumor cells, the activation of autophagy leads to the degradation of the serine protease granzyme B (GZMB) released by NK cells." (PMID 35795658, 2022). "IHC results confirmed markedly increased granzyme B expression in the tumor after therapy, whereas IHC of the tumor before therapy showed low PD-L1 expression levels." (PMID 35788116, 2022). "In mouse studies only, tumor NK cells have decreased expression of granzyme B and reduced proliferation." (PMID 35844626, 2022). "Meanwhile, the ratios of CD8+IFN-γ+ T, CD8+ IL-2+ T, CD8+TNF-α+ T, and CD8+Granzyme B+ T cells in the splenocytes of Cal/ICG@MPs with 808 nm laser irradiation-treated mice was significantly increased after tumor antigen restimulation." (PMID 35589680, 2022). "Granzyme B is a protein secreted by effector immune cells that can be released into the bloodstream, where it can affect the tumor targeting of 68Ga-grazytracer." (PMID 35788116, 2022). "These lymphocytes exert their action on tumor cells by secreting cytotoxic molecules, such as granzyme B, perforin or IFNγ, to maintain antitumor immunity." (PMID 36429101, 2022). "A combination of cisplatin and vinorelbine in patients with NSCLC made tumor cells more responsive to MHC-guided perforin and granzyme-B mediated CTL attacks, mainly associated with the MHC I upregulation." (PMID 36003765, 2022).
tumor (continued). "Th9 cells mediated direct granzyme B-dependent cytotoxicity against tumor cells, had upregulated Eomes expression, and were hyperproliferative enabling them to have extended persistence in vivo." (PMID 36159781, 2022). "In tumor-free mice, most IVpos NK cells in the circulation were positive for granzyme B and perforin, while only a minor fraction of IVneg NK cells in the tumor-free lungs showed granzyme B/perforin expression." (PMID 36733396, 2022). "In fact, tumor-infiltrating CD8+ T cells from obese breast cancer patients display lower expression of granzyme B compared to T cells from lean patients." (PMID 36713558, 2022). "Acidic tumor microenvironments prevent Fas/FasL interactions and decrease perforin/granzyme B release from NK cells." (PMID 36068970, 2022). "The distribution of 64Cu-grazytracer was consistent with the location of granzyme B, as determined using immunofluorescence staining of adjacent tumor sections." (PMID 35788116, 2022). "For example, it elevates the amount of mannose‐6‐phosphate (M6P) receptors on tumor cells, which subsequently leads to more penetration of cytotoxic T cells (CTLs) into the tumor site by releasing granzyme B following the autophagy." (PMID 36419058, 2022). "Accordingly, soft CD133+ tumour-repopulating cells were found to be resistant to perforin and take up less granzyme B following interaction with T cells." (PMID 35401556, 2022). "Apigenin treatment produced stronger activation of anti-tumor CD8+ cytotoxic cells and greater production of anti-tumor cytokines IFNγ, TNFα, and granzyme B in the blood than luteolin." (PMID 36555392, 2022). "For example, IFNG and genes encoding cytolytic enzymes (GZMA, GZMB and PRF1) were relatively up-regulated in SCLC-I tumors, indicating that SCLC-I tumors are characterized by a high level of tumor-infiltrating lymphocytes with potential cytolytic activity." (PMID 36428693, 2022). "Mouse GzmB and Human GzmB both show enzymatic activity against caspase-3 and caspase-7, and both enzymes induce cell death in tumor cells from both species." (PMID 35163755, 2022). "For Vps4b we find that inactivation impairs autophagy, resulting in increased accumulation of CD8+ T cell-derived granzyme B and subsequent tumor cell lysis." (PMID 35379808, 2022). "The numbers and the levels of CD69, IFN-γ, and GZMB in tumor-infiltrating CD8+ T cells were increased in sgRad21 ID8Trp53–/– tumors compared with scramble sgRNA–carrying tumors." (PMID 36201246, 2022). "Next, to validate activation of the CD8+ T and NK cells, gene expression analysis of GZMa (granzyme a), GZMb (granzyme b) and Prf1 (perforins) showed a significant increase in tumours of mice treated with RGD4C.TPA.IL15IgK particles." (PMID 35758207, 2022). "CD8Low T cell showed enhanced ST2L and IL6ST (CD130) expression compared to CD8High T cells which expressed elevated KLRD1 (CD94) and granzyme B levels within the tumour microenvironment (TME)." (PMID 36504430, 2022). "Analysis of the tumor immune infiltrate showed that DMXAA monotherapy up-regulated production of anti-tumor cytokines (i.e., IFNγ, Granzyme B, and TNFα) in both CD8+ and CD4+ T cells, which was further enhanced by combining with olaparib therapy." (PMID 35641483, 2022). "Next, we assessed if tumor PGRN expression was associated with the cytotoxic activity of CD8+ cells, by including the cytotoxic marker granzyme B (GzmB) and MHCI molecule HLA-A in the mIF." (PMID 35013174, 2022). "Granzyme B released by NK cells cleaves GSDME to trigger pyroptosis while enhancing the function of tumor-infiltrating immune cells to delay tumor growth furtherly." (PMID 35462927, 2022). "At the same time, we found that GZMB secreted by tumor infiltrating CD8+T cells increased, indicating that the function of CD8+T cells were enhanced in the low-dose anti-VEGFR2 group." (PMID 36260222, 2022).